RNU2-1 (RNA, U2 small nuclear 1)
Synonyms: U2; RNU2
Gene: Small nuclear RNA gene on chromosome 17 (43,233,790 to 43,233,977, reverse strand). Ensembl gene ENSG00000274585.
Pathways (Reactome):
Gene expression (Transcription): RNA polymerase II transcribes snRNA genes
Gene Ontology:
Molecular function: pre-mRNA branch point binding
Biological process: mRNA branch site recognition
Cellular component: U2 snRNP
Diseases named in the same sentence as RNU2-1 in open-access papers:
RNU2-1 is named in the same sentence as 16 diseases in open-access papers, as found by Europe PMC text mining. Sharing a sentence is not in itself a finding about the gene and the disease. The quoted sentences say what the papers report.
breast carcinoma (2 papers, 2013 to 2025). "As we have previously identified another small nuclear RNA, U6 snRNA, as an important biomarker for breast cancer in both tumor and plasma samples, we included RNU2-1 in this study as a complementary marker for which evidence remains limited." (PMID 41283331, 2025). "In the present study, we focused specifically on snoRNA-related genes and one snRNA gene (RNU2-1) in breast cancer." (PMID 41283331, 2025). "In this study, we evaluated the expression of selected candidate snoRNAs, along with small nuclear RNA gene RNU2-1, in tumor and benign tissues, as well as plasma samples, from Czech population cohorts with invasive NST breast cancer, for which such data have so far been lacking." (PMID 41283331, 2025).
lung carcinoma (2 papers, 2013 to 2025). "In lung cancer, levels of several tumor-educated platelet small nuclear RNAs, including RNU2-1, were significantly decreased, and this downregulation was correlated with cancer progression, supporting its proposed tumor suppressor role, consistent with our observations." (PMID 41283331, 2025).
colon cancer (1 paper, 2022). "In this study, RNU2-1 was upregulated in UC, which indicated that UC patients were more prone to colon cancer." (PMID 36310619, 2022).
lymph node metastasis (1 paper, 2025). "Significantly lower expression of RNU2-1 was observed in lymph node metastasis-positive samples (n = 4) compared with negative samples (n = 14) (p = 0.0337), along with a trend toward lower levels of SCARNA2 (p = 0.0710) and SNORD15B (p = 0.0559), compared to LNM-negative samples." (PMID 41283331, 2025).
cancer (6 papers, 2022 to 2025). A tumor composed of atypical neoplastic, often pleomorphic cells that invade other tissues. "Functionality of miR-1246 derived from RNU2-1 transcript was confirmed, and therefore, independently of its origin, miR-1246 remains an important miRNA involved in cancer." (PMID 35954369, 2022). "Exosomal MiR-1246 may be a smaller degradation product of a component of the spliceosome U2 (RNU2-1) in human cancer cells." (PMID 38899393, 2024).
tumor (3 papers, 2022 to 2025). "RNU2-1 (U2 snRNA) is a small nuclear RNA involved in the study and was also proposed as a tumor suppressor." (PMID 41283331, 2025). "A trend toward downregulation was also observed for all other candidate tumor suppressors: RNU2-1 (p = 0.1599), SCARNA2 (p = 0.0627), SCARNA3 (p = 0.1194), and SNORD15B (p = 0.0742)." (PMID 41283331, 2025). "Of great significance, artificially decaying RNU2‐1 transcripts led to an increase in exosomal miR‐1246 level, which polarized macrophages into a tumor‐supporting type both in vitro and in vivo." (PMID 38342611, 2024). "SNORD94, SNORD15B, SCARNA3, and RNU2-1 snRNA were also indicated as putative tumor suppressors." (PMID 41283331, 2025). "Staging data supported the presumed tumor suppressor roles of SCARNA2, SNORD15B, and RNU2-1, showing their higher expression in early-stage samples compared with more advanced stages." (PMID 41283331, 2025). "In this validation, five genes (RNU2-1, SCARNA2, SNORD15B, SCARNA3, and SNORD94) were confirmed to be significantly downregulated in tumor samples, while two genes (SNORA68 and SNHG1) were upregulated compared with benign samples." (PMID 41283331, 2025). "Additional tumor-suppressive potential was demonstrated for SNORD94 (possibly also prognostic), SNORD15B, SCARNA3, and RNU2-1." (PMID 41283331, 2025). "Among these candidate tumor suppressors, SNORD94, RNU2-1, SCARNA3, SNORD15B, and SCARNA2 appeared among the most promising for further validation, as their dysregulation was high and provided consistent results." (PMID 41283331, 2025).
RNU2-1 also shares sentences with these, for which no sentence is quoted: chronic pancreatitis (1 paper); Epileptic encephalopathy (1); Hepatic steatosis (1); infection (1); neuroblastoma (1); neurodevelopmental disorder (1); pancreatic ductal adenocarcinoma (1); ReNU syndrome (1); steatosis (1); type 2 diabetes (1).